IL24 (interleukin 24)
Diseases named in the same sentence as IL24 in open-access papers (continued):
Sharing a sentence is not in itself a finding about the gene and the disease.
bacterial pneumonia (1 paper, 2014). Acute infection of the lung parenchyma caused by bacteria (e.g., Streptococcus pneumoniae, Haemophilus influenzae, Chlamydia pneumoniae, Mycoplasma pneumoniae, and Legionella pneumophila). "Enhanced Fas, Fap, Il24, and Tnfsf15 expression is observed following LIF depletion in animals with bacterial pneumonia, which could contribute to the increased apoptosis observed here." (PMID 25277705, 2014).
bone cancer (1 paper, 2019). A primary or metastatic malignant neoplasm affecting the bone or articular cartilage. "It was recently discovered that IL-10 and IL-24, a member of the IL-10 family, were effective in relieving neuropathic pain and bone cancer pain in rats by the promotion of β-endorphin synthesis." (PMID 30981281, 2019).
chronic asthma (1 paper, 2022). An asthma that is characterized by the development of persistent airway inflammation and recurrent attacks of breathlessness and wheezing, which vary in severity and frequency. "Similarly, the in vivo results showed that IL-24 was overexpressed in the airway epithelium of an HDM-induced chronic asthma model, and IL-24 silencing or IL-37 treatment could reverse EMT biomarker expression." (PMID 36100847, 2022). "We aimed to explore the effect and mechanism of IL-24 on EMT and to verify whether IL-37 could alleviate IL-24-induced EMT in chronic asthma." (PMID 36100847, 2022).
chronic kidney disease (1 paper, 2020). Impairment of the renal function secondary to chronic kidney damage persisting for three or more months. "We also demonstrated the increased production of Il19, Il20, and Il24 in the kidney samples from the different animal models of acute and chronic kidney disease." (PMID 32306980, 2020).
CNS demyelination diseases (1 paper, 2024). "Spinal cord IL-24 levels were also found to be significantly higher in wild-type mice than in IL-20RB−/− mice, suggesting that IL-24 plays a role in CNS demyelination diseases." (PMID 38737586, 2024).
dermopathy (1 paper, 2021). "Consistent with previously published studies, the abnormal expression of cytokines, such as IL-20 and IL24, was also found in the skin of patients with dermopathy." (PMID 33763026, 2021).
diabetic nephropathy (1 paper, 2020). "Indeed, increased serum level of IL-19 and IL-24 was demonstrated in diabetic nephropathy and lupus nephritis." (PMID 32306980, 2020).
endometrial carcinoma (1 paper, 2024). A malignant tumor arising from the epithelium that lines the cavity of the uterine body. "Overexpression of IL-24 inhibits cell proliferation, migration, and invasion in endometrial carcinoma, but increases cell apoptosis; thus, it inhibits endometrial cancer cell growth by inducing apoptosis through the mitochondrial internal signaling pathway." (PMID 38711526, 2024).
Ewing sarcoma (1 paper, 2025). A small round cell tumor that lacks morphologic, immunohistochemical, and electron microscopic evidence of neuroectodermal differentiation. "Patients with Ewing sarcoma showing high levels of CXCL10 had slightly better OS (p = 0.049), but IL-24 and CXCL5 levels had no prognostic significance." (PMID 41008853, 2025).
fibrosis (1 paper, 2020). the formation of excess fibrous connective tissue in an organ or tissue in a reparative or reactive process. "To understand the mechanisms leading to increased production of IL19, IL20 and IL24 in the injured kidney we investigated the effect of several fibrosis related factors on their expression in healthy and CKD-derived PBMCs, as well." (PMID 32306980, 2020).
Glucose intolerance (1 paper, 2025). Glucose intolerance (GI) can be defined as dysglycemia that comprises both prediabetes and diabetes. "In vivo experiments demonstrated that IL-24 intervention not only improved insulin resistance and glucose intolerance but also significantly reduced hepatic steatosis, accompanied by a restoration of serum metabolic parameters (i.e., blood glucose, lipids, uric acid)." (PMID 41288708, 2025).
Hepatic steatosis (1 paper, 2025). Steatosis is a term used to denote lipid accumulation within hepatocytes. "IL-24 intervention improved liver steatosis, inflammation, fibrosis, and insulin resistance in MASH mice." (PMID 41288708, 2025).
hyperglycaemia (1 paper, 2024). "This suggests that IL-22 signaling, and not IL-20 or IL-24 signaling, is associated with hyperglycaemia." (PMID 38811550, 2024).
Hyperkeratosis (1 paper, 2022). Hyperkeratosis is a histopathological term defining a thickened stratum corneum and may be present in many different skin conditions, with many possible overlaps. "Notably, IL-19 and IL-20 but not IL-24 induce hyperkeratosis in response to IL-23, suggesting that IL-24 does not appear to be associated with dysfunctional tissue responses." (PMID 35819408, 2022).
injury (1 paper, 2020). Damage inflicted on the body as the direct or indirect result of an external force, with or without disruption of structural continuity. "Taken together, hepatocyte IL-24 may function as a prognosis predictor for patients with acute liver injury." (PMID 31907348, 2020).
keratoconus (1 paper, 2022). A degenerative, structural disorder of the eye, characterized by a cone-shaped protrusion of the cornea. "Interestingly, NicheNet predicted that ImC-derived IL24 may induce the differential expression of MMP1 in keratoconus CSCs." (PMID 35821117, 2022).
kidney injury (1 paper, 2020). Trauma to the kidney. "However, only the renal expression of Il24 increased in the mouse model of LPS-induced acute kidney injury." (PMID 32306980, 2020).
laryngeal carcinoma (1 paper, 2014). Carcinoma that arises from the laryngeal epithelium. "In the present study, the human MDA-7/IL-24 gene was transfected into the human laryngeal cancer Hep-2 cell line and human umbilical vein endothelial cells (HUVECs) with a replication-incompetent adenovirus vector." (PMID 24527085, 2014). "In the present study, the human MDA-7/IL-24 gene was transfected into the human laryngeal cancer Hep-2 cell line and HUVECs with a replication-incompetent adenovirus vector." (PMID 24527085, 2014).
liver dysfunction (1 paper, 2025). "Future studies should explore how cytokine storms, immune dysregulation, and organ-specific factors like liver dysfunction may directly influence IL-24 synthesis and its role in antiviral responses." (PMID 40943325, 2025).
lung fibrosis (1 paper, 2022). "Another study showed that IL-24−/− mice were protected against bleomycin-induced lung fibrosis by reducing TGF-β1 production and M2 macrophage infiltration." (PMID 36100847, 2022).
lupus nephritis (1 paper, 2020). Glomerulonephritis in the context of systemic lupus erythematosus. "Moreover, positive correlation was demonstrated between serum IL-24 level and the severity of lupus nephritis and renal ischemic/reperfusion injury." (PMID 32306980, 2020).
mesothelioma (1 paper, 2025). A usually malignant and aggressive neoplasm of the mesothelium which is often associated with exposure to asbestos. "Taken together, our findings suggest that ICB is most effective in inflamed mesotheliomas harbouring high IL24/CCL19 expression, TLSs and low EMT." (PMID 40691143, 2025). "B-lymphocyte infiltration inferred by transcriptome deconvolution, was correlated with both IL24 and CCL19 and the ratio of IL24 to EMT was significantly higher in R- vs NR- mesotheliomas and was associated for response with an AUROC of 0.889, p = 0.001." (PMID 40691143, 2025). "Expression of interleukins IL17C, IL23A and IL24 were greater in R- vs NR-mesotheliomas; Benajmini-Hochberg adjusted P values < 0.05." (PMID 40691143, 2025).
metabolic syndrome (1 paper, 2015). A cluster of metabolic risk factors for CARDIOVASCULAR DISEASES and TYPE 2 DIABETES MELLITUS. "Because IL-22R1 can combine not only with IL-10R2 to act as a functional IL-22R complex but can also interact with IL-20R2 to form a receptor for IL-20 and IL-24, it is likely that IL-22R1 ligands other than IL-22 may play a role in ameliorating HFD-induced metabolic syndrome." (PMID 26064446, 2015).
metastatic cancers (1 paper, 2021). A carcinoma which has spread from the original site of growth to another anatomic site. "As we have tried to capture, MDA-7/IL-24 has significant potential as a therapeutic for multiple primary and metastatic cancers and exploiting these properties has significant potential to lead to effective and enduring therapies for cancer." (PMID 35008495, 2021).
oral candidiasis (1 paper, 2022). Infection of the mucosal lining of the mouth with the fungus Candida albicans. "One understudied pathway that may be important for modulating oral candidiasis is the IL-20 cytokine signaling pathway that employs keratinocyte IL-20RB receptors as ligands for IL-19, IL-20, and IL-24." (PMID 36225230, 2022).
periodontitis (1 paper, 2022). An acute or chronic inflammatory process that affects the tissues that surround and support the teeth. "The enrichment of TNFRSF21+ fibroblasts with high expression of CXCL1, CXCL2, CXCL5, CXCL6, CXCL13, and IL24 was detected in patients with periodontitis compared to healthy individuals." (PMID 35154475, 2022).
peripheral nerve injury (1 paper, 2024). Injury to a peripheral nerve. "Further support of this finding is that spinal interleukin-24 contributes to neuropathic pain after peripheral nerve injury." (PMID 38831315, 2024).
rhabdomyosarcoma (1 paper, 2024). A rare aggressive malignant mesenchymal neoplasm arising from skeletal muscle. "TXNDC5 induces rhabdomyosarcoma proliferation survival and migration by regulating interleukin-24 (IL-24), which has a wide range of anticancer activities and gradually be used in clinical therapy." (PMID 38629066, 2024).
sarcoma (1 paper, 2025). A usually aggressive malignant neoplasm of the soft tissue or bone. "It includes information on cytokines that have been poorly studied in sarcoma peripheral blood samples, such as IL-24, IL-27, CCL21, CXCL5, and CXCL14." (PMID 41008853, 2025). "The remaining analytes, IL-8, IL-10, IL-12 P40, IL-24, IL-27, and CXCL10 were found in similar plasma concentrations in both patients with sarcoma and healthy subjects." (PMID 41008853, 2025).
Sepsis (1 paper, 2023). Sepsis is defined as life-threatening organ dysfunction caused by a dysregulated host response to infection. "We demonstrated that combination of IL-8, IL-24 and CCL20 have the best value to identify NEC from sepsis or the severity of NEC." (PMID 36806964, 2023). "It worth noting that IL-8 and IL-24 were both differentially expressed between NEC and HC as well as NEC and sepsis, and between different severities of NEC." (PMID 36806964, 2023). "We found IL-24, CXCL1, TSLP and IL-8 were significantly different between the NEC and sepsis groups." (PMID 36806964, 2023). "Further analysis showed the combination of IL-8, IL-24 and CCL20 have the best prediction value for NEC and control (AUC = 0.947), NEC and sepsis (AUC = 0.838) and different severity of NEC (AUC = 0.842)." (PMID 36806964, 2023). "Among these biomarkers, IL-8 and IL-24 were significantly different between NEC and sepsis and between different severities of NEC, which indicates that IL-8 and IL-24 levels have better clinical application value in distinguish NEC from sepsis or in distinguish the severity of NEC." (PMID 36806964, 2023).
skin cancer (1 paper, 2025). "Collectively, our findings establish a critical role for Th2 immunity in cancer immunoprevention and highlight the Th2/IL-24 axis as an innovative target for skin cancer prevention and therapy." (PMID 39744942, 2025). "IL-24 was essential for calcipotriol-plus–5-FU immunotherapy to mediate skin cancer protection in vivo." (PMID 39744942, 2025). "Calcipotriol-plus–5-FU–mediated skin cancer prevention is IL-24–dependent." (PMID 39744942, 2025).
Skin rash (1 paper, 2025). A red eruption of the skin. "The elevation of Th2-Associated Cytokines (IL-5, IL-24) typically associated with allergic and atopic conditions could explain the allergic manifestations like skin rash and pruritus observed in the patient." (PMID 40557145, 2025).
urticaria (1 paper, 2024). A vascular reaction of the skin characterized by erythema and wheal formation due to localized increase of vascular permeability. "IgE-anti–IL-24 levels showed an association with disease activity, as assessed by the urticaria activity score and withreduced basophil counts." (PMID 38380314, 2024).
ZIKV infection (1 paper, 2022). "The downregulation of inflammatory genes CCL18, CCL19, CXCL6, CXCL9, IL6R, IL11, IL24, and Integrin Subunit Beta 3 (ITGB3) with ZIKV infection may reflect placental immune tolerance." (PMID 35304593, 2022).
tumor (215 papers, 2006 to 2026). "Based on the data mined from published literature, we assembled IL-24-regulated signaling events linked to its immunoregulatory and anti-tumor activities." (PMID 40661937, 2025). "The data imply that the overexpression of IL24 enhances the activation of apoptotic mechanisms, potentially through intrinsic pathways, leading to increased tumor cell susceptibility to exosome-mediated cytotoxicity." (PMID 40076725, 2025). "Downregulation of IL24 has been associated with multiple cancer types, and its tumor-suppressive properties are attributed to its ability to induce apoptosis and inhibit tumor cell growth." (PMID 38456941, 2024). "In a phase I trial, intra-tumoral injection of Ad-mda-7, an adenovirus vector encoding IL-24, induced extensive apoptosis in tumor cells, yielding substantive clinical benefits in 44% of participants." (PMID 39664443, 2024). "Studies indicate that loss of Mda-7/IL-24 protein expression correlates with cancer progression and further reinforces the concept that Mda-7/IL-24 functions as a tumor suppressor." (PMID 37280571, 2023). "The overexpression of IL-24 can suppress the growth of a broad spectrum of tumor cells by causing apoptosis through the regulation of intracellular and extracellular signaling mediators." (PMID 36742134, 2023). "Another example is the bactofection of the gene encoding interleukin-24 in a gastric cancer model; it led to tumor regression mediated by proinflammatory cytokines, the activation of apoptosis, and angiogenesis disruption." (PMID 36077761, 2022). "The tumor-suppressive cytokine melanoma differentiation-associated gene-7/interleukin-24 (MDA-7/IL-24) inhibits tumor growth, angiogenesis, metastasis and invasion of different types of cancers and has been promisingly tested in a Phase I/II clinical trial." (PMID 31906510, 2020). "Melanoma differentiation-associated gene-7/interleukin-24gene (MDA-7/IL-24) is a unique tumor suppressor gene, which promotesselective apoptosis of cancer cells." (PMID 32023055, 2020). "IL-24 is also known as melanoma differentiation-associated-7 because of its tumor suppression function." (PMID 29471827, 2018). "Intratumoral injection of MDA-7/IL-24 caused an increase in tumor infiltrating, IFN-γ-producing CD8+ T cells." (PMID 26474456, 2015). "Using a mammary gland specific, tet-inducible MDA-7/IL-24 transgenic mouse model crossed with MMTV-Her2/Neu transgenic mice, the authors show that MDA-7/IL-24 caused an inhibition of tumor development." (PMID 26474456, 2015). "All of these findings provide evidence that IL-24 inhibits multiple signaling pathways that are associated with tumor cell metastasis." (PMID 24377906, 2013). "The involvement of MDA-7/IL-24-induced apoptosis in tumor tissues was associated with endoplasmic reticulum (ER) stress and mitochondrial dysfunction and reactive oxygen species (ROS) production." (PMID 22629368, 2012). "IL-24 (melanoma differentiation-associated gene-7 (mda-7)), a member of the IL-10 cytokine family, possesses the properties of a classical cytokine as well as tumor suppressor effects." (PMID 20072629, 2010). "IL24, which was highly up-regulated in this dataset, was recently found to be up-regulated in tumor-associated stromal cells as well." (PMID 20021671, 2009). "The molecular mechanisms underlying IL-24-iMSCs in exerting anti-tumor effect were also explored." (PMID 32015693, 2020). "Analogous examples include engineering OVs to encode interleukins, such as IL-12 or IL24, that function as inflammatory stimuli to promote immunological infiltration of the tumor microenvironment, which can strengthen efficacy when used in addition to other tumor therapeutics." (PMID 33172438, 2020). "We investigated whether interleukin (IL)-24, a tumor suppressor, inhibits GLI1 and the associated DDR pathway in human NSCLCs." (PMID 31783569, 2019).